MEIS1 (Meis homeobox 1)
Diseases named in the same sentence as MEIS1 in open-access papers (continued):
Sharing a sentence is not in itself a finding about the gene and the disease.
myeloid leukemia (12 papers, 2007 to 2024). A clonal proliferation of myeloid cells and their precursors in the bone marrow, peripheral blood, and spleen. "The MEIS1 gene is also associated with myeloid leukaemia and restless leg syndrome 7 (a sleep-wake disorder)." (PMID 30120083, 2018). "The Meis1 gene encodes a TALE-family transcription factor that was first identified as a common retroviral integration site in BXH2 murine myeloid leukemia." (PMID 24498346, 2014). "In hematopoietic lineage, induction of myeloid leukemia by oncogenic homeobox transcription factor Meis1 was promoted by the addition of TAD." (PMID 39474350, 2024). "We used myeloid leukemias induced by the coexpression of Hoxa9 and Meis1 (Hoxa9/Meis1) as controls, since these genes recapitulate the disease while bypassing the upstream alterations that induce their overexpression." (PMID 32343715, 2020). "In the hematopoietic system, NUP98-HOXA9, an oncogenic partner of Meis1 in human myeloid leukemia, has also been shown to promote symmetric self-renewal of hematopoietic precursors." (PMID 26285139, 2015). "The Meis1 gene was first identified in myeloid leukemia using BXH2 mice." (PMID 33402862, 2020). "In addition, Meis2 is overexpressed in myeloid leukemia mice, resulting in the conclusion that MEIS1 and MEIS2 may have a parallel function in myeloid leukemia." (PMID 33402862, 2020). "TALE-class homeobox gene MEIS1 is a well-known oncogene aberrantly activated via KMT2A-fusion proteins in both lymphoid and myeloid leukemias." (PMID 36233173, 2022). "Meis1 is known to be coexpressed with homeobox genes, such as HOXA5, 7 and 9 in myelogenous leukemias." (PMID 17615543, 2007). "For instance, targeting EZH2 could deplete HOXA9 and Meis1 levels in THP1 cells and disrupt the biological synergy between the two genes in inducing myeloid leukemia." (PMID 25944687, 2015). "In the same manner, other reports show that the trimer complex MEIS1-PBX-HOXA9 and the dimer PBX-HOXA9 did not transactivate a reporter gene with PBX-HOXA9 binding sites in myeloid leukemia." (PMID 35637493, 2022).
ovarian carcinoma (12 papers, 2014 to 2023). A malignant neoplasm originating from the surface ovarian epithelium. "Ovarian cancer studies have shown that Meis1, Meis2, nuclear, and total cytoplasmic Pbx1–4 RNA expressions, and protein contents are higher than normal tissue in both nuclear and cytoplasmic locations." (PMID 33402862, 2020). "Moreover, MEIS1 has been shown to play a key role in the early stages of ovarian cancer through its involvement and regulation of T-cell chemo-attraction." (PMID 33402862, 2020). "Our results also suggest that targeting Meis1 in skin tumors could be a powerful strategy for the treatment of skin cancer as well as other epithelial tumors in which Meis1 appears to have an oncogenic role, such as endometrial and ovarian cancers." (PMID 25013928, 2014). "In female reproduction, MEIS1 was not only confirmed to be an important regulator of embryonic development, but also proved to regulate the transcription of multiple ovarian cancer-related chemokines, which is expected to be a positive prognostic indicator for ovarian cancer." (PMID 36834999, 2023). "MEIS1 triggers chemokine expression and involvement in CD8+ T-lymphocyte infiltration in early-stage ovarian cancer." (PMID 37719881, 2023). "We found that SGC0946 and EPZ004777 inhibited expression of DOT1L-targeted genes (MEIS1 and NANOG) in a dose-dependent manner, a finding which confirms the inhibitory effect of DOT1L activity in ovarian cancer cells." (PMID 29712898, 2018). "In fact, MEIS1 was presented in human GCs at essentially all stages of follicular development; however, in addition to regulating ovarian cancer, its role in the ovary and GCs are not clear." (PMID 36834999, 2023). "In addition, qRT-PCR results revealed the expression of CDK4, FGF5, MEIS1, and TES genes was significantly increased in CFP1-deleted ES-2 ovarian cancer cells." (PMID 35864225, 2022). "The transcription factor myeloid ecotropic viral integration site 1 (MEIS1) binds to a specific region on the promoter of the CXCL7 gene and induces the synthesis and secretion of CXCL7 in cells of ovarian cancer, thus triggering the recruitment of CD8+ T lymphocytes in ovarian cancer." (PMID 35837284, 2022). "Interactions between MEIS1 and PBX1–3 are involved in the early stages of ovarian cancer." (PMID 33402862, 2020).
acute lymphoblastic leukemia (11 papers, 2011 to 2025). Leukemia with an acute onset, characterized by the presence of lymphoblasts in the bone marrow and the peripheral blood. "Moreover, MEIS1 knockdown inhibited DNA replication in acute lymphoblastic leukemias (ALL) through regulation of involved genes in cell cycle process." (PMID 31090196, 2019). "For example, TALE homeobox gene MEIS1 and its target gene HOXA9 in turn are aberrantly activated by KMT2A fusion proteins in myeloid leukemia and B-cell progenitor acute lymphoid leukemia (BCP-ALL)." (PMID 39202339, 2024). "Furthermore, we identified aberrant expression of IRX2, IRX3 and MEIS1 in patients with B-cell precursor acute lymphoblastic leukemia (BCP-ALL) which originates from early B-cell progenitors." (PMID 36233173, 2022). "MEIS1 and HOXA5 were enriched in Thy1 cells and may maintain the stemness of T precursor cells as the upregulation of them were reported in acute lymphocytic leukemias." (PMID 38318192, 2024).
glioma (9 papers, 2015 to 2026). A benign or malignant brain and spinal cord tumor that arises from glial cells (astrocytes, oligodendrocytes, ependymal cells). "ELF1 can activate MEIS1 transcription to promote glioma progression, and it is also involved in the regulation of the relapsing cell state in melanoma and the phenotypic transition." (PMID 40025540, 2025). "A recent study reported that MEIS1 inhibits apoptosis of glioma cells by upregulating GFI1 expression." (PMID 36834999, 2023). "A recent report also shows a positive correlation between MEIS1 and ELF1 levels in glioma patients and the upregulation of MEIS1 through ELF1 binding to its promoter sequence." (PMID 35624144, 2022). "Mechanistically, circ0001361 may regulate glioma progression via hsa-miR-525-5p/MEIS1, suggesting its potential as a therapeutic target for glioma intervention strategies." (PMID 41984870, 2026). "In glioma, Meis1 expression is high, while Meis2 expression is low." (PMID 33402862, 2020).
insomnia (9 papers, 2019 to 2025). A sleep disorder characterized by difficulty in falling asleep and/or remaining asleep. "We identified 62 variants linked to shared genetics of MDD and insomnia symptoms, with signals near MEIS1, RP11-6N13.1, OLFM4, HEXIM1, and TCF4 being the strongest." (PMID 34680902, 2021). "Leave‐one‐out plots revealed that the rs113851554 variant in MEIS1 flipped the Egger regression effect estimate for insomnia on migraine." (PMID 33125193, 2020). "However, other reports suggest that the association of MEIS1 with insomnia only comes from the inclusion of RLS cases." (PMID 31551905, 2019). "Recent genetic studies of insomnia using cases from the UK biobank showed that MEIS1 has the strongest association signal, suggesting MEIS1 may be a shared genetic risk factor for RLS and insomnia." (PMID 31551905, 2019). "Furthermore, clinical insomnia associations highlighted two loci that were primarily associated with RLS, MEIS1 consistent with earlier studies, and PRMT6, as well as five additional shared loci and one locus specific to clinical insomnia, PAX8 (PP = 0.8)." (PMID 41332830, 2025). "Some reports argue that the phenotype overlap could only drive some, and not all of the MEIS1's association with insomnia, thus suggesting that MEIS1 has a pleiotropic effect on RLS and insomnia." (PMID 31551905, 2019). "Notably, this MEIS1 SNP is also a strong risk factor for RLS and may reflect heterogeneity in the insomnia discovery GWAS based on undiagnosed RLS or pleiotropy at this locus." (PMID 35538198, 2022). "First, a study has reported that MEIS1 shows a pleiotropy effect on RLS and insomnia." (PMID 34680902, 2021).
lung carcinoma (8 papers, 2015 to 2023). "The relationships of two other TFs including MEIS1 and TBX5 with lung cancer are unclear." (PMID 26035298, 2015).
breast carcinoma (7 papers, 2011 to 2023). "Taken together, these data indicate that MEIS1 and associated factors may demonstrate an oncogenic function in breast cancer development and progression." (PMID 33402862, 2020). "Correlation analysis indicated that Meis1 level was positively correlated with SNORD3A level in breast cancer tissues." (PMID 32382150, 2020). "We further found that Meis1 expression was downregulated in breast cancer cells compared with the normal mammary cell line MCF10A." (PMID 32382150, 2020). "High expression of Meis1, Tmem25, and Reps2 is a determining factor for evaluating the probability of relapse and survival of breast cancer." (PMID 33402862, 2020). "Together these results suggested that Meis1 transcriptionally regulates SNORD3A expression in breast cancer cells." (PMID 32382150, 2020). "We used a registration-free online service to generate Kaplan–Meier plots and found that high Meis1 expression in breast cancer predicted a better outcome in breast cancer, while high miR-185-5p predicted a worse outcome." (PMID 32382150, 2020). "Our findings indicate that Meis1-regulated SNORD3A specifically sensitizes breast cancer cells to 5-FU via enhancing UMPS expression." (PMID 32382150, 2020). "Bioinformatics analysis combined with experimental validation indicated that Meis1 was downregulated in breast cancer and positively regulated SNORD3A expression at the transcriptional level." (PMID 32382150, 2020). "The expression of Meis1, along with transmembrane protein 25 (Tmem25) and Reps2, has been suggested to be a marker for breast cancer prognosis." (PMID 33402862, 2020). "SNORD3A is downregulated in breast cancer resulting from Meis1 downregulation." (PMID 32382150, 2020). "In breast cancer, estrogen receptor induces Meis1 and Forkhead box P3 (Foxp3) upregulation." (PMID 33402862, 2020). "Clinically, low Meis1 level predicts a poor prognosis in breast cancer patients." (PMID 32382150, 2020). "Predicted regulatory element sequences for NANOG, CREB1, CPBP, BEN, PREB-1, SOX10, and POU2F1 (OCT1) POU6F1 and MEIS1 were highly enriched in the promoter regions of the tissue context dependent genes suggesting their possible roles in stem cells proliferation in HER2-regulated breast cancer tissue." (PMID 25428913, 2015). "We performed IHC staining of Meis1 and UMPS proteins in breast cancer tissues that were examined by ISH." (PMID 32382150, 2020). "High SNORD3A transcript and Meis1 and UMPS protein levels predicts a better outcome, but high miR-185-5p level predicts a worse outcome in breast cancer patients receiving 5-FU-based chemotherapy." (PMID 32382150, 2020). "In breast cancer tissues, SNORD3A level positively correlates with Meis1 and UMPS protein levels, whereas miR-185-5p level negatively correlates with UMPS protein level." (PMID 32382150, 2020). "As expected, Meis1 and UMPS protein were expressed at low levels in approximately 77.78% and 65.28% breast cancer specimens, respectively." (PMID 32382150, 2020). "Importantly, high SNORD3A transcript and Meis1 and UMPS protein levels predicts a better outcome, but high miR-185-5p level predicts a worse outcome in breast cancer patients receiving 5-FU-based chemotherapy." (PMID 32382150, 2020). "Meis1 level was also decreased in breast cancer tissues from the cohort compared with non-cancerous tissues." (PMID 32382150, 2020). "Moreover, Meis1 overexpression transcriptionally promotes SNORD3A expression, and Meis1 is downregulated in breast cancer cells and tissues." (PMID 32382150, 2020). "We hypothesize that MEIS1 methylation in the stroma may originate from infiltrating T-lymphocytes, similar to the methylation of CDH1 in breast cancer." (PMID 24244575, 2013).
Ewing sarcoma (7 papers, 2019 to 2023). A small round cell tumor that lacks morphologic, immunohistochemical, and electron microscopic evidence of neuroectodermal differentiation. "Of note, it was reported that MEIS1 is involved in superenhancer associated gene expression in combination with EWS-FLI in Ewing sarcoma." (PMID 34707247, 2022). "In Ewing sarcoma, for instance, transcription factor MEIS1 was identified as a super-enhancer-associated gene, which co-operates with EWS-FLI1 oncoprotein to directly co-bind super-enhancer regions of APCDD1, and activates the transcription of APCDD1, thereby inhibiting cell apoptosis." (PMID 36834999, 2023). "Through a series of cellular phenotypical assays and in vivo experiment, we characterized MEIS1 in Ewing sarcoma as both a driver of cell proliferation and survival." (PMID 30496486, 2019). "Further investigation based on the biological attributes of super-enhancers identified MEIS1 as a novel oncogenic transcription factor that played a key pro-survival role in Ewing sarcoma, via activating the transcription of APCDD1 cooperatively with EWS-FLI1." (PMID 30496486, 2019). "Among these 147 super-enhancer-associated transcripts, we were particularly interested in MEIS1, because the intensity of its super-enhancer ranked first in SKNMC cells, and it had prominent expression profiles in Ewing sarcoma." (PMID 30496486, 2019). "Further to understand the function of MEIS1 in the biology of Ewing sarcoma, ChIP-seq was performed using MEIS1 antibody in A673 cells." (PMID 30496486, 2019). "It has been shown that MEIS1 is an important factor for cell proliferation in Ewing sarcoma cells." (PMID 33402862, 2020). "In summary, the current study provides comprehensive analysis of super-enhancer-mediated transcriptional dysregulation of Ewing sarcoma, and identifies MEIS1 as a novel super-enhancer-driven oncogene, which co-operates with EWS-FLI1 in transcriptional regulation." (PMID 30496486, 2019). "The MEIS1 ChIP-seq raw data generated in A673 Ewing sarcoma cell line is available on NCBI GEO under the accession number ‘GSE109477’; the RNA-seq raw data of A673 and SKNMC cells upon DMSO or THZ1 treatment are also available on GEO, under the accession number ‘GSE117485’." (PMID 30496486, 2019). "In addition, we identified the super-enhancer-associated APCDD1, which was uniquely expressed at high levels in Ewing sarcoma, as a novel pro-growth gene transcriptionally activated by MEIS1 and EWS-FLI1 in a co-operative fashion." (PMID 30496486, 2019). "The biological relevance of MEIS1 in Ewing sarcoma was next assessed." (PMID 30496486, 2019). "Collectively, these data strongly suggested that MEIS1 is a progrowth factor in Ewing sarcoma." (PMID 30496486, 2019). "Moreover, it was reported that MEIS1 functions together with EWS-FLI1 in Ewing sarcoma." (PMID 33402862, 2020). "In addition, immunoblotting confirmed high sensitivity of MEIS1 to THZ1 treatment in Ewing sarcoma." (PMID 30496486, 2019). "Through comprehensive analysis, the authors identified MEIS1 as a SE-driven oncogene that synergizes with EWS-FLI1 in transcriptional regulation and plays a key role in pro-survival in Ewing sarcoma." (PMID 32714929, 2020). "Through integrative analysis, we identify MEIS1 as a super-enhancer-driven oncogene, which co-operates with EWS-FLI1 in transcriptional regulation, and plays a key pro-survival role in Ewing sarcoma." (PMID 30496486, 2019). "Similar to MEIS1 silencing, APCDD1 depletion reduced cell proliferation and anchorage-independent growth of Ewing sarcoma cells." (PMID 30496486, 2019). "Besides, they identified that the SE-related gene APCCD1, a downstream target of MEIS1 and EWS-FLI1, was also a novel tumor-promoting factor for Ewing sarcoma." (PMID 32714929, 2020).
Ewing sarcoma (continued). "Considering our observation from ChIP-seq experiment that the HOX motif was strongly enriched in MEIS1-interacting DNA sequence, future exploration of the functional interplay between MEIS1 and HOX genes in the context of Ewing sarcoma will be of great interest." (PMID 30496486, 2019). "Moreover, our data suggested that MEIS1 and EWS-FLI1 co-operatively activate APCDD1 transcription, thereby promoting the malignant phenotype of Ewing sarcoma cells." (PMID 30496486, 2019).
sarcoma (6 papers, 2019 to 2025). A usually aggressive malignant neoplasm of the soft tissue or bone. "MEIS1::NCOA2/1 fusion sarcoma is a rare, recently recognized spindle cell neoplasm defined by a characteristic gene fusion involving MEIS1 and NCOA2 or, less commonly, NCOA1." (PMID 41463261, 2025). "Several of the identified MLS- and EWS-specific transcription factors are implicated in FET sarcoma oncogenesis; for example, increased gene expression of the EWS-specific transcription factors HOXD11, SOX6, MEIS1, and E2F6 were reported to be involved in EWS malignancy." (PMID 40988026, 2025). "The silencing of Meis1 in the xenograft model was found to suppress tumor size in sarcoma." (PMID 33402862, 2020). "Taken together, Meis1 and Hoxa9 may function as an oncogene in sarcoma." (PMID 33402862, 2020). "No specific line of differentiation was found by immunohistochemical staining, and an RNA-based fusion panel revealed a MEIS1::NCOA2 fusion, at which point a diagnosis of Low-Grade Undifferentiated Sarcoma with MEIS1::NCOA2-Rearrangement was rendered." (PMID 38678288, 2024).
anemia (5 papers, 2015 to 2025). A reduction in the number of red blood cells, the amount of hemoglobin, and/or the volume of packed red blood cells. "Shared biological mechanisms, such as the MEIS1 gene, which is linked to both anaemia and sleep disturbances, or altered brain blood flow associated with sleep disturbances and anaemia, may explain these associations." (PMID 40317866, 2025). "Meis1 is essential for normal hematopoiesis, as was indicated by Meis1 mutant mice having an internal hemorrhage, liver hypoplasia, and anemia." (PMID 33402862, 2020). "Various assays showed defects in erythropoiesis providing explanation for anemia in Meis1 mutants." (PMID 26545946, 2015). "Having observed anemia in Meis2-/- embryos we further pursued the possibility that Meis2 may influence embryonic hematopoiesis similarly to Meis1 that controls proliferation of hematopoietic stem cells in the fetal liver and is also essential for megakaryocyte viability." (PMID 26545946, 2015).
colon cancer (5 papers, 2013 to 2023). "In conclusion, MEIS1 methylation is associated with BRAFp.V600E in colon tumors and accompanied by a decrease of MEIS1 gene expression." (PMID 24244575, 2013). "In conclusion, BRAFp.V600E colon tumors showed significant MEIS1 promoter methylation, which was associated with decreased MEIS1 gene expression." (PMID 24244575, 2013). "We show that MEIS1 methylation occurred more frequently in BRAFp.V600E mutated colon tumors, and that it corresponded with decreased MEIS1 gene expression." (PMID 24244575, 2013). "BRAFp.V600E-associated MEIS1 methylation was associated with decreased gene expression of the full length MEIS1 transcript and a truncated isoform, MEIS1D27 in tumors and colon cancer cell lines." (PMID 24244575, 2013). "MEIS1 expression in both normal and colon tumor samples was variable, possibly reflecting tissue heterogeneity and inter-individual variation." (PMID 24244575, 2013). "Using a discovery cohort of 19 right-sided colon tumors and paired normal tissue, we found MEIS1 as the most significantly hypermethylated gene promoter associated with BRAFp.V600E mutation." (PMID 24244575, 2013). "MEIS1 promoter methylation was accompanied by relatively lower levels of MEIS1 gene expression in the five BRAFp.V600E colon tumors compared with their corresponding normal paired tissue (ratios between 0.07 and 0.59)." (PMID 24244575, 2013). "Moreover, MEIS1 inhibition is observed in BRAF-mutant colon tumors." (PMID 35743243, 2022).